ATM (ATM serine/threonine kinase)
Diseases named in the same sentence as ATM in open-access papers (continued):
Sharing a sentence is not in itself a finding about the gene and the disease.
neuroblastoma (57 papers, 2007 to 2025). Neuroblastoma (NB) is the most common solid, extracranial childhood tumor. "In neuroblastoma cells, IR activates ATM, causes JNK to be phosphorylated by TAK1 in a manner that then activates AP-1 transcription factor, which in turn increases the transcriptional activity of the PRNP promoter by interacting with AP-1 binding sites." (PMID 36980514, 2023). "In neuroblastoma, ATM, a DNA damage response-associated gene located on 11q22-23, has been linked to tumorigenicity." (PMID 37020276, 2023). "Our study revealed the molecular mechanism underlying ATM heterozygosity in neuroblastomas and elucidated that ATM inactivation enhances the susceptibility of neuroblastoma cells to olaparib treatment." (PMID 37020276, 2023). "ATM mutation is well documented as a determinant of sensitivity to ATR and a recent study showed that low ATM protein levels were associated with ATR inhibitor cytotoxicity in a panel of neuroblastoma cell lines." (PMID 36077823, 2022). "Non-silent SNVs (2–6 per tumour) in cancer-related genes (HRAS, ALK and ATM) occurred exclusively in high-risk neuroblastomas and were clonal in a subset of patients but also spatially or temporally heterogeneous in others." (PMID 34815394, 2021). "Cytogenetic aberrations involving chromosome 11q, which contains cancer-associated genes such as ATM and Chk1, have been implicated in neuroblastoma." (PMID 29641431, 2018). "It was reported that the N-Myc-induced miR-421 down regulated ATM (Ataxia telangiectasia-mutated gene) expression, establishing an N-Myc/miR-421/ATM pathway which contributed to N-Myc-induced carcinogenesis in neuroblastoma." (PMID 27016414, 2016). "Should the function of ATM be compromised in somatic cells, this can enable the acquisition of tumorigenic mutations, often seen in cancers including breast cancer, neuroblastoma and colorectal cancer." (PMID 38933336, 2024). "Although these observations indicate that ATM deficiency contributes, at least in part, to malignant transformation of hematopoietic cells due to increased chromosome instability, the mechanisms underlying neuroblastoma pathogenesis remain elusive." (PMID 34069817, 2021). "Finally, we included probes covering additional genes previously found mutated in neuroblastoma, and with potential relevance for neuroblastoma tumor biology or targeted therapies, including ATM and ATR." (PMID 34442335, 2021). "Inhibitors of miR-421 in neuroblastoma and HeLa cells led to an increased expression of ATM protein." (PMID 41065894, 2025). "Over-expression of miR-421 in neuroblastoma or HeLa cells reduces ATM protein, resulted in S-phase cell cycle checkpoint changes and an increased sensitivity to IR resulting in creating a cellular phenotype similar to cells derived from A-T patients." (PMID 41065894, 2025). "Although phase 1 clinical trials of ATM-3507 (Anisina) for the treatment of neuroblastoma were terminated due to toxicity, the development of more potent and selective Tpm3.1/3.2 inhibitors is being pursued." (PMID 41268543, 2025). "A previous study demonstrated that the downregulation of ATM by miR-421 promotes neuroblastoma progression." (PMID 39338204, 2024). "It is documented that the microRNA-421 mediates downregulation of ATM gene via overexpression of MYCN transcriptional factor in neuroblastoma; however, this relation in pulmonary blastoma needs to be discovered through large cohort studies." (PMID 38235566, 2024). "ShRNA lentiviral vectors were used to knockdown ATM expression in SK-N-AS and SK-N-SH neuroblastoma cell lines." (PMID 37020276, 2023). "We used the human SH-SY5Y neuroblastoma cell line, introduced various ATM shRNAs via lentiviral transduction, and produced a stable ATM-KD cell line that achieved high ATM protein- and mRNA-reduction for further analysis." (PMID 37830614, 2023). "AZD0156 is an ATM inhibitor with potential anti-neoplastic activity that targets ALT positive neuroblastomas." (PMID 37046606, 2023).
neuroblastoma (continued). "For validation of these mouse findings in the human species, a knockdown of ATM in neuroblastoma SH-SY5Y cells was employed, taking into account the previous usefulness of such human in vitro modelling projects in autophagy and chemoresistance studies of ATM." (PMID 37830614, 2023). "A marked downregulation of FANCD2 expression was also observed in shRNA-mediated ATM-knockdown neuroblastoma cells." (PMID 37020276, 2023). "Complete loss of ATM suppressed the expression of DNA repair-associated molecules FANCD2 and RAD51 and induced DNA damage in neuroblastoma cells." (PMID 37020276, 2023). "It was reported that JCPyV-infected human neuroblastoma IMR-32 cells accumulate in the G2 phase of the cell cycle by activating ATM- and ATR-mediated checkpoint pathways that form part of the cell’s DNA damage response (DDR)." (PMID 37815349, 2023). "Validation experiments with stressors were performed in human neuroblastoma cells, where ATM was localised only to cytoplasm, similar to the brain." (PMID 37830614, 2023). "Recent research has indicated that ALT neuroblastoma chemotherapy resistance occurs via ATM activation and is reversible with the ATM inhibitor AZD0156." (PMID 37096801, 2023). "The use of differential detergents to achieve subcellular fractionation of the old adult mouse cerebellum and of SH-SY5Y neuroblastoma line, localised ATM mainly to the cytosol, both in unstressed and in stressed conditions, in WT cells and ATM-KD cells." (PMID 37830614, 2023). "Due to the loss of multiple genes involved in HRR, including ATM, PARP inhibitors have been proposed as therapeutic agents for neuroblastoma patients with 11q deletion." (PMID 34508175, 2021). "Preclinical studies show that ATM mutated neuroblastoma cells also succumb to apoptosis when treated with PARP inhibitors and neuroblastomas with 11q deletion are extremely sensitive to conventional chemotherapy combined with PARP inhibitors." (PMID 33916788, 2021). "Synthetic lethality is explored with PARP inhibitors in several cancers such as ATM-deficient tumors from breast and ovaries, aggressive prostate cancers in combination with ATR inhibitors, and high-risk neuroblastomas under ATR inhibition." (PMID 34359720, 2021). "For example, ATM expression in neuroblastoma cell lines is suppressed by miR-421, which can be induced by proto-oncogene transcriptional factor N-Myc, making neuroblastoma cells more sensitive to radiotherapy." (PMID 33918762, 2021). "miR-421 was found to suppress ATM expression in LA-N-1 and LA-N-5 neuroblastoma cells in vitro by targeting the 3’-UTR of ATM transcripts, with ATM 3’-UTR rescuing the radioresistance phenotype caused by miR-421." (PMID 32182776, 2020). "We have used antisense morpholino oligonucleotide (AMO-miR421) to modulate miR-421 and ATM expression in neuroblastoma cells." (PMID 30657058, 2019). "Genomic alterations, such as loss and single nucleotide variants, in the ATM gene and other DNA damage response (DDR)-associated genes were found in nearly half of neuroblastoma and neuroblastoma-derived cell lines, particularly in advanced stages." (PMID 30684955, 2019). "Here, we report that haploinsufficiency of ATM in neuroblastoma correlates with lower ATM expression, event-free survival, and overall survival." (PMID 26053094, 2015). "In SK-N-SH, CLB-Ga and GI-ME-N human neuroblastoma cells, stable ATM silencing promotes neuroblastoma progression in soft agar assays, and in subcutaneous xenografts in nude mice." (PMID 26053094, 2015). "In order to study the mechanism related to apoptosis and genotoxic effect of MPTQ on neuro 2a neuroblastoma cells, we utilized an antibody specific for phosphorylated ATM that recognizes activated mouse ATM (phophorylated at Ser1983)." (PMID 23824039, 2013).
neuroblastoma (continued). "Growth inhibition was accompanied by an increase in both cell size and the percentage of cells with 4N DNA content, suggesting that the ATM-3507-treated cells were arrested in the G2/M phase of the cell cycle and were unable to undergo cytokinesis, as has been observed in neuroblastoma cells." (PMID 41268543, 2025). "ATM activation is a current indicator of resistance to chemotherapy agents temozolomide and irinotecan in ALT neuroblastoma cells; thus, inhibition of Ataxia telangiectasia mutated (ATM) could sensitize these tumors to treatment." (PMID 37046606, 2023). "Collectively, we presume that MYCN-mediated neuroblastoma cell proliferation may largely depend on DNA-PKcs in coordination with ATM; however, if the activation of DNA-PKcs is impaired, LIG4 could complement their repair ability." (PMID 37240360, 2023). "Moreover, miR-421 has been demonstrated to bind to the 3′ UTR of ATM and downregulate its expression in neuroblastoma, HeLa, and CRPC cells." (PMID 37812088, 2023). "Because there is no mechanism ensuring their complete inactivation, our group and others revealed that synthetic lethality could be induced by treatment with a PARP inhibitor in neuroblastoma cells with ATM haploinsufficiency." (PMID 34796286, 2021). "As in neuroblastoma, haploinsufficiency of the ATM tumor suppressor gene may be a candidate driver gene for 11q region loss." (PMID 33567541, 2021). "Reportedly, ATM silencing promotes neuroblastoma progression independently of MYCN amplification." (PMID 34796286, 2021). "Regarding concomitant treatment with targeted drugs and CHK1 inhibitors, we previously demonstrated that an inhibitor of ATM or DNA-dependent protein kinase (DNA-PK) potentiates CHK1 inhibitor-mediated growth suppression in MYCN-amplified neuroblastoma cell lines." (PMID 34069817, 2021). "The combination of ATM inhibition with chemotherapy is currently the most promising option for ALT neuroblastoma, although regimens combining cytotoxic chemotherapy agents and inhibition of master upstream regulators of DNA damage repair such as ATM are likely to be prone to significant toxicities." (PMID 32375866, 2020). "ATM gene has been shown to be downregulated by miR-421 in neuroblastoma and HeLa cells." (PMID 24616890, 2014). "Taken together, activation of ATM suggests MPTQ as a genotoxic agent which might have induced DNA DSBs in neuro 2a neuroblastoma cells and might have engaged cells to activate other factors associated with apoptosis." (PMID 23824039, 2013). "We recently provided evidence that the FOXO3-ATM complex also overcomes epigenetic silencing of the caspase-8 gene in human neuroblastoma cells by activating the ATM downstream target CREB which in turn triggers methylation-independent activation of the caspase-8 promoter." (PMID 23801966, 2013). "Since MPTQ is a structural analogue of ellipticine and DNA damage was seen in MPTQ treated neuroblastoma cells, activation of ATM was hypothesized." (PMID 23824039, 2013). "When its effect was studied in xenograft models, it was shown that some neuroblastoma cell lines were sensitive to Olaparib, particularly those with mutations in genes associated with the DNA damage response (DDR) pathway, of which the ATM gene is thought to be the master regulator." (PMID 40426729, 2025). "ATM loss occurs in high stage neuroblastoma without MYCN amplification." (PMID 26053094, 2015). "Thus, activation of ATM strongly support our finding on the induction of DNA double strand breaks in MPTQ treated neuroblastoma cells and might play a key role in the activation of apoptotic cascade by activating downstream target proteins." (PMID 23824039, 2013). "AZD0156, an ATM inhibitor, has been used to treat ALT neuroblastomas and overcomes chemotherapy resistance." (PMID 38910895, 2024). "The ATM inhibitor AZD0156 has shown selective toxicity in melanoma cells, neuroblastoma, and preclinical models of colorectal cancer." (PMID 38910895, 2024).
neuroblastoma (continued). "To elucidate its molecular mechanism of action, we established ATM-inactivated NGP and CHP-134 neuroblastoma cell lines using CRISPR/Cas9 genome editing." (PMID 37020276, 2023). "These include ATR and ATM inhibitors, such as the ATM inhibitor AZD0156 in ALT positive neuroblastoma." (PMID 36833275, 2023). "Thus, our observation of IP3R abundance reduction below 50% in ATM-KD neuroblastoma cells emerges from the transcriptome profile validation work as arguably the most important molecular event, which might explain the preferential affection of cerebellar neurons." (PMID 37830614, 2023). "JCPyV LT was shown by others to mediate cell cycle arrest at the G2/M phase in a human neuroblastoma cell line through the activation of DDR checkpoint proteins, ATM, and ATR." (PMID 37815349, 2023). "Other synthetic lethalities include the ATM inhibitor, KU60019, or Top1 inhibitor, irinotecan, in ATRX-deleted neuroblastoma." (PMID 34359720, 2021). "The ATM inhibitor AZD0156 was found to be synergistic with temozolomide and irinotecan therapy in both in vitro and in-vivo models of ALT neuroblastoma." (PMID 32375866, 2020). "We have previously demonstrated that N-Myc overexpression can down-regulate ATM expression via a human microRNA, miR-421, in MYCN-amplified neuroblastoma cells." (PMID 30657058, 2019). "For example, ATM and ATR activation leads to G2 arrest in JCPyV-infected human neuroblastoma cells and oligodendrocytes." (PMID 22952448, 2012). "Moreover, ATM depletion induces proteasomal degradation of FANCD2 and sensitizes neuroblastoma cells to PARPis54." (PMID 40038300, 2025). "A previous report demonstrated that simultaneous inhibition of Chk1 and ATM increases cell death in NB-39-nu and SK-N-BE neuroblastoma cells, which are not generally responsive to Chk1 inhibitors." (PMID 36765693, 2023). "Substantial evidence revealed that the frequency of allelic loss at 11q23 was inversely related to MYCN amplification in neuroblastomas, a common region of deletion that harbours a series of proteins that play a central role in the DSB repair pathways such as ATM, MRE11, and H2AFX." (PMID 37240360, 2023). "If so, a combination of ATM and ATR inhibitors may prove more efficacious against ALT+ neuroblastomas compared to either inhibitor alone." (PMID 35053227, 2022). "Subsequently, it was reported that ALT+ neuroblastoma cell lines exhibit activation of the ATM pathway, rather than the ATR pathway, and that an ATM inhibitor reverses their chemoresistance against temozolomide + SN-38 (the active metabolite of irinotecan)." (PMID 35053227, 2022). "Here, we report that human neuroblastoma cell lines engineered to express TrkA/NTRK1 in tightly controlled systems fail to activate the G2/M cell cycle checkpoint upon irradiation, which recapitulates the effects of ATM or ATR inhibition." (PMID 34885133, 2021). "Whilst the attenuation of tumour cell growth was observed in DDR-defective neuroblastoma cell lines treated with Olaparib, this effect was not seen in ATM-competent ones, suggesting that pre-existing defects in DNA damage repair pathways increases tumour sensitivity to PARPi." (PMID 40426729, 2025). "Thus, flattened cells without processes that are predominant for ATM-KD cells could reflect a shift in neuroblastoma cell populations towards S-type cells." (PMID 37830614, 2023).
neuroblastoma (continued). "In turn, KIT expression showed a positive correlation with the ERK cell survival signaling pathway and negative with ATM cell G2-M cell cycle arrest pathway, thus suggesting a possible role of KIT in neuroblastoma cell proliferation, survival, and control of G2/M cell cycle checkpoint." (PMID 35887076, 2022). "A more proliferative state of the ATM-KD cells may result in reduced expression of many neurotransmission factors, potentially explaining the drastic downregulation of OPRM1 in ATM-KD neuroblastoma cells, as opposed to increased Oprm1 in the old ATM-null cerebellum." (PMID 37830614, 2023).